BRAF (B-Raf proto-oncogene, serine/threonine kinase)
Diseases named in the same sentence as BRAF in open-access papers (continued):
Sharing a sentence is not in itself a finding about the gene and the disease.
colorectal cancer (continued). "Evidence has been provided that IDH1/2 mutants are more frequent in colorectal cancers showing CpG island methylator phenotype, often concurrent with KRAS/BRAF mutations, although with a lower allelic frequency." (PMID 37064137, 2023). "Whereas BRAF testing will identify approximately half of sporadic MMRd colorectal cancer cases, MLH1 promoter methylation will definitionally identify sporadic MMRd colorectal cancer." (PMID 38344144, 2023). "As described in the example of BRAF-targeted therapy for colorectal cancer, it is possible that a combination of targeted agents can inhibit cancer growth even if individual targeted therapies do not work." (PMID 38069146, 2023). "Shi-r used a deep artificial neural network to predict the gene status of KRAS, NRAS, and BRAF in patients with liver metastasis of colorectal cancer." (PMID 38201314, 2023). "Collectively, the results of this study provide strong evidence for the therapeutic potential of SJ-C1044 in RAS or BRAF mutant colorectal cancers." (PMID 37504287, 2023). "Younger colorectal cancer patients are less likely to have MSI-H or BRAF mutations than older bowel cancer patients, and BRAF mutation status is highly correlated with MMR protein expression." (PMID 37427134, 2023). "Our results raise the question of why and how Fn infection is enriched in colorectal cancer with SSP phenotypes including MSI-H, MLH1 hypermethylation, and BRAF mutations, and, independently, KRAS mutations." (PMID 37772997, 2023). "Mutations of the BRAF oncogene, primarily BRAFV600E, are detected in up to 10% of patients with colorectal cancer." (PMID 37466791, 2023). "We categorized tumors with APC wild-type and BRAF or KRAS mutation as serrated, a subtype of colorectal cancer that derive from serrated polyps via an alternate pathway usually with absence of APC mutation." (PMID 37057593, 2023). "BRAF V600E and KRAS mutations that occur in colorectal cancer (CRC) define a subpopulation of patients with an inferior prognosis." (PMID 37240418, 2023). "In colorectal cancer, the incidence of RAS wild-type is reported to be 40–50%, BRAF V600E mutation about 10%, dMMR/MSI about 15%, TMB-H about 11%, and HER2-positive 2–11%." (PMID 37760533, 2023). "We recently found that the depletion of CROCC in BRAF-mutant colorectal cancer cells promotes the acquisition of rhabdoid features." (PMID 37239344, 2023). "Colorectal cancer (CRC) cells harboring KRAS or BRAF mutations show a more-malignant phenotype than cells with wild-type KRAS and BRAF." (PMID 37972012, 2023). "Cancers frequently associated with a CIMP-high phenotype include colorectal cancer (CRC) and glioma, with BRAF (CRC) and IDH1 (glioma) mutations also associated with this phenotype, as well as with microsatellite instability in CRC42." (PMID 36928603, 2023). "As a second-line treatment for RAS/BRAF wild-type colorectal cancer, treatment regimens using anti-EGFR antibodies are recommended by regional guidelines as one of the standard treatments." (PMID 37760533, 2023). "Taken together, these results showed that MSI-H, BRAF mutations, MLH1 hypermethylation, and KRAS mutations are independently associated with Fn infection in colorectal cancer." (PMID 37772997, 2023). "The intrinsic chemoresistance of colorectal cancer involves the enhanced cellular efflux of chemotherapy drugs with mutations of various genes (KRAS, BRAF, EGFR) and changes in respective signaling pathways." (PMID 37373047, 2023). "Mutations that constitutively activate RAS, BRAF, or PIK3CA are most common among colorectal cancers with frequencies of 30–50%, 10–15%, and 10–20%, respectively." (PMID 37791907, 2023).
colorectal cancer (continued). "HER2-low colorectal cancer tumors are like HER2-zero tumors, with a lower proportion of perineural invasion, lower tumor stage and more RAS/BRAF mutation, compared with HER2-high tumors." (PMID 36672503, 2023). "CMS1 CRC, also known as MSI immune type, is the type in which most BRAF mutant colorectal cancers fall and usually has more immune cell infiltration." (PMID 37302081, 2023). "In a 190 colorectal cancer cohort, we identified seven somatic mutations in KRAS, NRAS and BRAF as well as five MSI loci (D2S123/D5S346/D17S250/BAT‐25/BAT‐26) simultaneously." (PMID 36583506, 2023). "Colo-205 is a colorectal cancer cell line that is also highly sensitive to BRAF inhibition and degradation." (PMID 38136350, 2023). "All colorectal cancer tumors harbored alterations in the WNT pathway regulator APC; 6 (60%) were KRAS mutated, which were mutually exclusive from BRAF V600E mutations [n = 2 (20%)]." (PMID 36426653, 2023). "One of those trials (FOCULM trial) about mFOLFOXIRI with or without cetuximab as conversion therapy in patients with RAS/BRAF wild-type unresectable liver metastases colorectal cancer showed the median OS of 33.2 months in the control group (mFOLFOXIRI only)." (PMID 37978547, 2023). "Background and Objectives: We aimed to investigate the role of Wnt2 expression in colorectal cancer (CRC) prognosis and evaluate its potential as a therapeutic target in BRAF-mutated CRC." (PMID 37374338, 2023). "In colorectal cancer, combined BRAF, EGFR, and MEK inhibition in patients resulted in modest improvement in response rates." (PMID 37917191, 2023). "The last guidelines for managing colorectal cancer emphasize the importance of biomarkers (MSI status, KRAS, and BRAF mutations) in advanced stages (stage II-III-IV)." (PMID 38201408, 2023). "Combined BRAF + MEK inhibition is FDA approved for BRAF V600E-mutant solid tumors except for colorectal cancer." (PMID 36801912, 2023). "With the development of sequencing technology, tumor-related genes are being increasingly identified, and RAS, BRAF, and PIK3CA mutations are being detected in colorectal cancer." (PMID 38201315, 2023). "Guided by various clinical trials for colorectal cancer, we selected and tested combinations of BRAF/EGFR, BRAF/MEK, MEK/WNT, and BRAF/WNT inhibitors at their IC50 concentrations against CRC2 spheroids." (PMID 37791907, 2023). "Many common alterations associated with advanced colorectal cancer were detected, including loss of function events in APC (OMIM 611731), and hotspot KRAS (OMIM 190070) and BRAF (OMIM 164757) variations (V600E, D595G, and G469A)." (PMID 38051531, 2023). "This study underscores the significance of early BRAF testing at the time of colorectal cancer diagnosis." (PMID 38136294, 2023). "We assessed the clinicopathological features and prognostic values of KRAS, NRAS, BRAF, and DNA mismatch repair status in colorectal cancer (CRC) to provide real-world data in developing countries." (PMID 36862900, 2023). "One of the main findings presented here is that incidence of Fn infection is significantly high in colorectal cancer exhibiting not only SSP phenotype including MSI-H, MLH1 hypermethylation or BRAF mutations but also KRAS mutations." (PMID 37772997, 2023). "For these considerations, this study aimed to assess the prognostic value of PD1/PD-L1 and BRAF proteins expression in colorectal carcinoma by immunohistochemical analysis." (PMID 36673047, 2023). "The highest frequency of gene rearrangements was seen in KRAS/NRAS/BRAF wild-type colorectal carcinomas (53/204 (26%))." (PMID 37686416, 2023). "The current study concluded that overexpression of BRAF protein in colorectal carcinoma is a poor prognostic pathological marker." (PMID 36673047, 2023).
colorectal cancer (continued). "In sporadic colorectal carcinomas displaying the MSI phenotype, MLH1 hypermethylation and BRAF p.V600E mutations frequently co-occur, indicating a possible causal relationship between BRAF mutations and MLH1 loss." (PMID 37190216, 2023). "Some of the commonly identified mutations associated with targeted therapies include, e.g., mutations in BRAF in cutaneous melanoma; KRAS, BRAF, and NRAS in colorectal cancer; and EGFR mutations and ALK and ROS1 gene rearrangements in lung adenocarcinomas." (PMID 35627184, 2022). "To date, the CE-IVD IdyllaTMKRAS Mutation Test and the IdyllaTMNRAS-BRAF Mutation Test have been developed to detect KRAS, NRAS, and BRAF mutations in colorectal cancer patients." (PMID 35474548, 2022). "In a patient with stage IV BRAF V600E colorectal cancer that progressed on standard therapies, off-label use of this triple combination was well tolerated and effective, achieving tumor control for almost 8 months." (PMID 36058945, 2022). "BRAF oncogene was found in more than 50% of skin cutaneous melanoma as well as other cancers such as colorectal cancer and papillary thyroid cancer." (PMID 36531226, 2022). "In colorectal cancer, BRAF-V600E targeted therapies have been less successful, but BRAF-mutant metastatic colorectal cancer is associated with a worse prognosis." (PMID 35087199, 2022). "We also analyzed 508-case TCGA and 63-case CPTAC colorectal cancer cohorts for all members of the GALNT enzyme family, the mucin family, as well as KRAS and BRAF mutations." (PMID 35692787, 2022). "Recent papers have implicated oncogenic mutations in BRAF and RNF43 in the serrated neoplasia pathway of right-sided colorectal cancer." (PMID 36275468, 2022). "In colorectal cancer the combination of the BRAF inhibitor encorafenib with the EGFR monoclonal antibody cetuximab has shown promising results and was approved for the treatment of patients with BRAF V600E mutations." (PMID 36275468, 2022). "A similar phenomenon was observed in BRAF-mutant colorectal cancer cells, in which FAK activation enhances Wnt/β-catenin pathway activation to promote BRAF inhibitor resistance." (PMID 35163650, 2022). "BRAF V600E-mutant colorectal cancer (CRC) is a rare subtype of colorectal cancer with poor prognosis." (PMID 36130926, 2022). "From 157 patients with lung or colorectal cancer, 29 patients (18%) showed positive ctDNA liquid biopsies, with genetic mutations in EGFR (n = 9), BRAF (n = 3), neuroblastoma rat sarcoma virus (NRAS) (n = 1), and Kirsten rat sarcoma virus (KRAS) (n = 16)." (PMID 36497340, 2022). "In contrast, in the TCGA cohort, colorectal cancers with wild type BRAF had TMB above 200 in 16.8% of cases when PIK3CA was mutant and in 7.3% of cases when PIK3CA was wild type." (PMID 36079062, 2022). "In the DFCI cohort, colorectal cancers with wild type BRAF had TMB above 200 in 35% of cases when PIK3CA was mutant and in 18.5% of cases when PIK3CA was also wild type." (PMID 36079062, 2022). "These cell lines and the cell line NCI-H508 also possess deletions of PRKN, encoding for ubiquitin ligase parkin, which is the only recurrent deletions in BRAF/PIK3CA double mutant colorectal cancer cell lines." (PMID 36295658, 2022). "Constitutive activation of the RAS–RAF–MEK–ERK1/2 pathway (hereafter, ERK1/2 pathway), resulting from mutational activation of BRAF or KRAS proteins, occurs in the majority of melanomas and colorectal cancers." (PMID 36267209, 2022). "BRAF and PIK3CA are oncogenic kinases commonly mutated in colorectal cancers and can be targeted through small molecule kinase inhibitors." (PMID 36079062, 2022).
colorectal cancer (continued). "The differences of biomarkers between colorectal cancer and its metastases have been compared, including KRAS/BRAF mutation and MSI status, indicating the importance of testing mutations in peritoneal metastasis and treating methods." (PMID 36614904, 2022). "For example, RANBP2, a binding protein of RAN (RAS related nuclear protein), a small GTPase of the RAS family, has been proposed as essential for survival of BRAF V600E mutant colorectal cancer cells and cells with a similar genomic signature." (PMID 36295658, 2022). "Mutation in TIMM8B occurred in only one subject with colorectal cancer (TMB of 52.14 mut/Mb and concurrent BRAF V600E mutation), and the patient died within one month of PD-1 inhibitor monotherapy." (PMID 36358851, 2022). "In BRAF-mutant colorectal cancer, BRAF inhibitors trigger resistance through an alternative mechanism, as EGFR signaling is upregulated." (PMID 35510953, 2022). "Both BRAF and KRAS are oncogenes that are commonly mutated in colorectal cancer, and mutations in these genes are often considered mutually exclusive." (PMID 35383926, 2022). "BRAF mutant colorectal cancers show a higher prevalence of chromosomal stability as determined by low Aneuploidy Score (AS) and low Fraction of Genome Altered (FGA) score." (PMID 36079062, 2022). "The author also observed that in colorectal cancer samples, KMT2D mutations co-occur more frequently than expected with BRAF mutations." (PMID 36275468, 2022). "They pointed out that specific epidemiological characteristics of colorectal cancer patients were associated with KRAS and BRAF mutations." (PMID 36119474, 2022). "These drugs benefit patients with BRAF mutant colorectal cancers but responses are rather brief, and progression is the rule." (PMID 36295658, 2022). "The ultimate goal is to discover new therapeutic opportunities beyond the currently available BRAF inhibitors, which are currently the only approved drugs, in combination with anti-EGFR therapies, for colorectal cancers with V600E mutations." (PMID 36295658, 2022). "The guidelines and studies generally recommended cetuximab therapy only to patients with RAS and BRAF wild-type colorectal cancer." (PMID 36465411, 2022). "COLO320DM is an EGFR-negative human colorectal cancer cell line with wild-type KRAS/BRAF, which is an ideal cell model for generating stable EGFR mutant cell lines." (PMID 35907884, 2022). "It is worth noting that only 10% of the patients that participated in BEACON had MSI high cancers compared with a prevalence of MSI exceeding 50% in BRAF mutant colorectal cancers of the TCGA and DFCI cohorts." (PMID 36079062, 2022). "Mutations in PIK3CA are the most frequent mutations in the receptor tyrosine kinase-initiated pathways in colorectal cancers with BRAF mutations, as the even more frequent KRAS mutations are mutually exclusive with BRAF mutations." (PMID 36295658, 2022). "In contrast, PIK3CA mutations are encountered in colorectal cancers with either KRAS or BRAF mutations with an equal or higher prevalence than in cancers with wild type KRAS and BRAF." (PMID 36295658, 2022). "Anti-BRAF/EGFR therapy was recently approved for the treatment of metastatic BRAFV600E colorectal cancer (mCRCBRAF-V600E)." (PMID 36097219, 2022). "The presence of inactivating mutations in RNF43, a negative regulator of WNT, in tumor cells predicts improved response rates and survival outcomes in patients with metastatic BRAFV600E colorectal cancer treated with anti-BRAF/EGFR therapy." (PMID 36097219, 2022). "Colorectal cancer cell line models recapitulate the presence of BRAF and PIK3CA mutations as encountered in clinical colorectal cancer samples, and also duplicate the frequent presence of MSI in these cases." (PMID 36295658, 2022).
colorectal cancer (continued). "In BRAF mutant colorectal cancer cells, BRAF inhibitor treatment increased FAK activation leading to increased Wnt pathway signaling." (PMID 35525274, 2022). "On the other hand, BRAF wild type colorectal cancers show higher rates of chromosomal instability (CIN) as determined by higher AS and FGA scores." (PMID 36079062, 2022). "The two V600E BRAF mutant/PIK3CA wild type colorectal cancer cell lines, LS411N and CL34, that are MSI high have consistently a high mutation count." (PMID 36295658, 2022). "This suggests that overexpression of HER2 is more likely to occur in patients with left hemicolorectal cancer and KRAS/NRAS/BRAF WT colorectal cancer." (PMID 35365123, 2022). "The findings provide evidence that HPSE promotes cell proliferation by regulating cell cycle progression via the AKT/p27Kip1/Cyclin E2 axis in BRAF V600E-mutant colorectal cancer." (PMID 36130926, 2022). "In various genomic information-based cancer studies, such as those based on TCGA, the BRAF V600E mutation was found in various cancers, such as NSCLC and colorectal cancer." (PMID 35893795, 2022). "Second, vitamin C selectively kills KRAS and BRAF mutant colorectal cancer cells by targeting glyceraldehyde 3-phosphate dehydrogenase." (PMID 35956413, 2022). "Unfortunately, BRAF inhibitors can induce other cancer types as well, such as head and neck-, colorectal cancer or glioblastoma." (PMID 36213163, 2022). "Here, using BRAFV600E mutant colorectal cancer cells we show that de novo BRAF amplifications are acquired in selumetinib-treated populations with remarkable efficiency." (PMID 36267209, 2022). "We demonstrate that MEKi resistance arises predominantly through de novo BRAF amplifications in colorectal cancer cells." (PMID 36267209, 2022). "We tested plasma samples from the Erbitux Metastatic Colorectal Cancer Strategy (ERMES) phase III trial of FOLFIRI+Cetuximab in first-line treatment of RAS/BRAF wild-type mCRC." (PMID 35205799, 2022). "BRAF V600E mutations are downstream targets of the RAS signaling pathway and are altered in 10% of colorectal cancer (CRC) patients; these mutations are also mutually exclusive with the KRAS mutation." (PMID 36230757, 2022). "The combination was tested in vivo in seven patient-derived xenograft (PDX) models (five colorectal carcinoma and two papillary thyroid carcinoma models) with different KRAS, BRAF, and NRAS mutations." (PMID 35075200, 2022). "In colorectal cancers (CRC), somatic mutations in KRAS, BRAF, or ERBB receptors occur in ~ 60 % of patient tumors." (PMID 34233735, 2021). "For patients with NMA, additional factors beneficial to survival, except for the right‐side colorectal cancer and BRAF‐mutant status, favored the cetuximab group over the bevacizumab group." (PMID 33939281, 2021). "Alternatively, treatment of BRAF mutant colorectal cancer models with MAPK inhibitors stimulated WNT pathway through the activation of cytoplasmic focal adhesion kinase (FAK) or depletion of AXIN1 protein, resulting in the stabilization of β-catenin." (PMID 33821796, 2021). "Data from published full exome sequences of colorectal cancer have suggested that GNAS mutations are quite often accompanied by mutations in KRAS and/or BRAF." (PMID 35141142, 2021). "The results were consistent with several previous studies, including one that determined BRAF can be used as a prognostic indicator of colorectal cancer." (PMID 33622273, 2021). "In colorectal cancer, mutations of the KRAS and BRAF genes are quite common and can contribute to the activation of cell signaling pathways that lead to cell proliferation and differentiation." (PMID 34063682, 2021).